ERBB2 (erb-b2 receptor tyrosine kinase 2)
Diseases named in the same sentence as ERBB2 in open-access papers (continued):
Sharing a sentence is not in itself a finding about the gene and the disease.
tumor (continued). "We additionally performed immunohistochemistry analysis for erbB2 protein staining (in parallel sections) in 13 esophageal primary tumor tissue samples, four of the tissues of which were included in the plasma DNA dataset previously analyzed." (PMID 21481261, 2011). "EGFR belongs to the ErbB family of receptor tyrosine kinases (which also includes ERBB2 and ERBB3) and members of this family have been implicated both in EMT induction, and in tumor progression." (PMID 21816090, 2011). "High expression level of ERBB2 has been significantly correlated with increased tumor invasion, metastasis, resistance to chemotherapy, and poor prognosis of patients." (PMID 21689422, 2011). "Among Erbb receptors, Erbb2 and Erbb4 mRNA levels decreased with malignant progression and became barely detectable at the tumor stage." (PMID 20975924, 2010). "Tumor regression following IGF-IR transgene downregulation was studied to model the effects of ErbB2 overexpression during the use IGF-IR-directed therapeutics." (PMID 20825649, 2010). "Average tumor size at this time point was 4-fold greater in the RM11A+Dox/ErbB2 cells compared to RM11A+Dox cells." (PMID 20825649, 2010). "Human MSC expressing an artificial receptor that binds to erbB2, a tumor cell marker, were obtained by transduction with genetically modified adenoviral vectors encoding an artificial receptor (MSC-AR)." (PMID 20500878, 2010). "This is particularly important because currently the application of ERBB2-targeting drugs is limited to patients whose tumours express high levels of the ERBB2 protein or show amplification of the ERBB2 gene." (PMID 20859285, 2010). "In vivo, it was observed that ErbB2 conferred a more rapid tumor onset and tumor incidence was also elevated as indicated by the number of mammary glands injected that actually developed tumors." (PMID 20825649, 2010). "The expression of ErbB-2 also appeared heterogenous with only discrete areas of the tumor displaying an intense (2+) staining often cell membrane associated." (PMID 20565727, 2010). "Our results suggest that upregulation of ErbB2 is one such mechanism through which tumor cells gain this capacity." (PMID 20825649, 2010). "Statistically significant associations were observed among the nuclear expression of MBP-1 and ErbB2 status, Ki-67 expression, node status and tumor grade." (PMID 20886042, 2010). "This study has revealed that even in the presence of vast IGF-IR overexpression, a modest increase in ErbB2 can augment tumor establishment in vivo, mediate resistance to IGF-IR downregulation and facilitate metastasis." (PMID 20825649, 2010). "ErbB2 conferred an accelerated tumor onset and increased tumor incidence after injection of RM11A cells into the mammary glands of syngeneic wild type mice." (PMID 20825649, 2010). "The presence of ErbB2 impaired tumor regression following IGF-IR transgene downregulation (doxycycline withdrawal)." (PMID 20825649, 2010). "Transient expression of the erbB2 tumor marker in the lungs of hCAR transgenic mice was achieved by i.v. injection of an adenovirus encoding the erbB2 antigen (AdCMVerbB2)." (PMID 20500878, 2010). "To this end, we have created MSCs that express an artificial receptor (AR) that binds to erbB2, a frequent marker of tumor cells (MSC-AR)." (PMID 20500878, 2010). "We then analyzed the effect of cannabinoids on tumor progression in a well established and clinically relevant animal model of ErbB2-driven metastatic breast cancer, the MMTV-neu mouse." (PMID 20649976, 2010). "MSC-AR properties were tested in vitro in cell binding assays and in vivo using two model systems: transient transgenic mice that express human erbB2 in the lungs and ovarian xenograft tumor model." (PMID 20500878, 2010).
tumor (continued). "Using Ki67 staining to examine proliferation our data suggested that proliferation is only significantly affected by ErbB2 overexpression shortly after tumor cells colonize the mammary tissue (4 d post injection but not 14 d post injection)." (PMID 20825649, 2010). "Basal-like tumours generally showed a lower degree of methylation than the other subclasses (luminal A, luminal B, ERBB2 and normal-like)." (PMID 20338046, 2010). "Expression of erbB2 tumor marker in the mouse lungs ensures its easy accessibility to systemically injected cells and direct cell-marker contact." (PMID 20500878, 2010). "The average tumor area was approximately 4-fold higher in the RM11A+Dox/ErbB2 tumors compared to RM11A+Dox tumors at this time point." (PMID 20825649, 2010). "A number of factors are known to influence the response to AC chemotherapy, including tumour stage, grade, number of lymph nodes involved, oestrogen receptor (ER), progesterone (PR) and ERBB2 expression." (PMID 20179710, 2010). "In contrast, MBP-1 expression strongly correlated with the node status (P = 0.0002), tumor grade (P<0.0001) and expression levels of ErbB2 (P = 0.0001) and Ki67 (P = 0.0096) proteins." (PMID 20886042, 2010). "Previous work carried out in transgenic EGFR and ERBB2-mutant mice showed substantial tumor regression when mice were treated with a combination of BIBW-2992 and rapamycin targeting mTOR (or more specifically TORC1)." (PMID 20111714, 2010). "Differently, using the anti-ErbB-2 antiserum cross reacting with the murine receptor resulted in a faint stain of the cytoplasm and rarely in staining of the membrane of the tumor cells." (PMID 20565727, 2010). "Tumor areas characterized by intense membrane ErbB-2 expression (A) display significantly lower htid level (B, C), thus, demonstrating the inverse correlation of the expression of the two tumor relevant molecules and implying their functional link." (PMID 20565727, 2010). "Although MSCs have the native ability to home to tumors, we attempted to enhance their tumor-targeting abilities by adding an additional tumor-targeting element: an artificial receptor (AR) with specificity to erbB2." (PMID 20500878, 2010). "In particular, ErbB2 overexpression correlates, for instance, with tumor size, increased metastatic potential, and higher histological grade, implying that ErbB2 confers a strong proliferative and survival advantage to tumor cells." (PMID 20649976, 2010). "Upon quantitative analysis, a statistically significant 1.3-fold increase in Ki67 positivity was observed in the RM11A+Dox/ErbB2 tumor cells compared to RM11A+Dox tumor cells." (PMID 20825649, 2010). "We tested on trastuzumab-resistant cells two novel human anti-tumour immunoconjugates engineered in our laboratory by fusion of a human anti-ErbB2 scFv, termed Erbicin, with either a human RNase or the Fc region of a human IgG1." (PMID 20051960, 2010). "Cyclin D1 has previously been shown to be a major mediator of ErbB2-induced tumor cell proliferation and oncogenesis." (PMID 19754954, 2009). "Our data demonstrate a significant correlation between the transcription levels of hCAP18 and ERBB2 genes in ER-positive as well as in ER-negative tumours." (PMID 19183447, 2009). "The best-performing group of patients revealed by this gene signature had tumours predominantly of the luminal A, normal-like or ERBB2 molecular subtypes." (PMID 19904269, 2009). "Overexpression of ErbB-2 predicts for aggressive tumor behavior, resistance to some cytotoxic and antihormonal therapies, and poor overall survival." (PMID 20024517, 2009). "The expression of hCAP18 correlated closely with that of ERBB2 and with the presence of lymph node metastases in oestrogen receptor-positive tumours." (PMID 19183447, 2009). "In the transgenic tumours, a decrease of phosphorylated p185 ERBB2 was found whereas a band of 65 kDa was increased in intensity, indicative of ERBB2 degradation." (PMID 19183447, 2009).
tumor (continued). "While ERBB2 represents a distinct expression tumor subtype in multiple independent cohorts, it is noteworthy that most ERBB2 (HER2+) cell lines clustered in the luminal subtype." (PMID 19582160, 2009). "The miRNA signatures have been correlated with clinicopathological and prognostic parameters such as tumor size, nodal involvement, vascular invasiveness, ErbB2, estrogen receptor status and chemotherapy resistance." (PMID 19664288, 2009). "For example, oncogenic activation of the receptor tyrosine kinase ERBB2 contributes to tumour cell resistance to hypoxia by inducing the α5β1 integrin fibronectin receptor, which increases cell adhesion and survival." (PMID 19173736, 2009). "ERBB2 mRNA and protein expression were downregulated below detection limit leading to a macroscopically complete tumour remission within 14 days." (PMID 18454161, 2008). "Downregulation of ERBB2 leads to a rapid and macroscopically complete tumour remission within 14 days." (PMID 18454161, 2008). "The A5-linker-ML3.9 bs-scFv also exhibits significantly greater in vivo targeting of ErbB2‘+’/ErbB3‘+’ tumours than derivative molecules that contain only one functional arm targeting ErbB2 or ErbB3." (PMID 18841159, 2008). "Recently, we have shown that dephosphorylation of ERK1/2 is relevant for tumour remission after ERBB2-blocking therapy." (PMID 18454161, 2008). "All signatures proved valuable for prognosticating risk of recurrence in the ER+ subgroups and less so for the ER- and ERBB2+ tumours." (PMID 22275966, 2008). "The reduction in signalling downstream of ErbB2 when Akt is activated suggest a possible mechanism by which tumour cells can become resistant to ErbB2-targeted therapies, necessitating therapies that target oncogenic signalling events downstream of ErbB2." (PMID 18700973, 2008). "Immunoblotting with an anti-ErbB2 antibody demonstrated that the level of ErbB2 protein was dramatically increased in tumours of both origins compared with normal mammary tissue from the same mouse, from FVB mice or from myr-Akt1 transgenic mice." (PMID 18700973, 2008). "It should also be considered that human ERBB2 was expressed in our mouse tumour model, since Herceptin is directed against the human oncogene." (PMID 18454161, 2008). "Even in marginally positive tumors ErbB2 staining was relatively weak (compare with staining in a tumor derived from a transgenic MMTV.neu mouse)." (PMID 18808719, 2008). "We have shown a strong dephosphorylation of ERK1/2 after Atc-mediated downregulation of ERBB2 using the same mouse tumour model as in the present work." (PMID 18454161, 2008). "Other groups have developed bsAb-based molecules that simultaneously target two tumour-associated antigens such as EGFR and insulin growth factor receptor (IGFR) or carcinoembryonic antigen (CEA) and ErbB2." (PMID 18841159, 2008). "This concept suggests that trastuzumab should be used only for the subset of tumours whose growth depends on the oncogenic signal of ERBB2." (PMID 18454161, 2008). "We used a mouse model that allows anhydrotetracycline (ATc)-controlled downregulation of ERBB2 in tumour tissue." (PMID 18454161, 2008). "The interaction of trastuzumab with ERBB2 in our mouse tumour model is illustrated by a strong decrease in membrane localisation within 6 h after administration of trastuzumab." (PMID 18454161, 2008). "Similar observations were found in ErbB2 transgenic model, with rapid re-growth of tumor after cessation of therapy." (PMID 18570671, 2008). "Overexpression of ErbB2 oncoprotein has been shown to correlate with tumour aggressiveness in various tumours." (PMID 18781152, 2008). "Binding of ALM to ErbB2‘+’/ErbB3‘+’ cells mediates inhibition of tumour cell growth in vitro by effectively targeting the therapeutic anti-ErbB3 A5 scFv." (PMID 18841159, 2008).
tumor (continued). "First, MVM2 cells and MDA-MB-468 were used to approximate normal tissues that express only ErbB2 or only ErbB3, respectively, and BT-474 cells represented ErbB2‘+’/ErbB3‘+’-positive tumours." (PMID 18841159, 2008). "In MMTV-Neu mice, the introduction of a targeted deletion of the β4 cytoplasmic domain revealed that β4 integrin promotes tumor progression cooperating with ErbB-2 signaling." (PMID 18270579, 2008). "This underlines the need to direct trastuzumab only to this subset of tumours whose growth depends on ERBB2 signalling." (PMID 18454161, 2008). "The reduced Src activation indicated by low Tyr416 phosphorylation levels in the bitransgenic tumours is corroborated by the reduced phosphorylation of ErbB2 at Tyr877, which is mediated by Src." (PMID 18700973, 2008). "Women whose breast tumours stain 3+ for ERBB2 (meaning that strong complete membrane staining is seen in more than 10% of tumour cells) are most likely to respond to trastuzumab." (PMID 18454161, 2008). "ER-/ERBB2- and ERBB2+ tumours were characterized by high proliferation, whereas ER+ tumours were more heterogeneous and further subdivided into ER+/low/luminal A and ER+/high/luminal B subtypes." (PMID 22275966, 2008). "The extent of activating phosphorylation of ErbB2 was lower in the bitransgenic tumours than in the c-ErbB2 tumours, demonstrated by using phosphospecific antibodies to two different phosphorylation sites in ErbB2, Tyr877 and Tyr1248." (PMID 18700973, 2008). "ERBB2 mRNA and protein expression can efficiently be downregulated by administration of anhydrotetracycline (ATc) to tumour-bearing mice." (PMID 18454161, 2008). "In the present study, we made the surprising observation that a ‘ERBB2-dependent’ tumour can be completely resistant to trastuzumab." (PMID 18454161, 2008). "The expression of ER, PR, and erbB2/neu was available in 67 cases: ER or PR positivity was documented in 43 (64.2%) and 37 (55.2%) cases, respectively, whereas 35 patients (52.2%) had erbB2/neu-overexpressing (2+/3+ score) tumours." (PMID 18493232, 2008). "This led to the concept that the subgroup of trastuzumab-sensitive tumours is ‘ERBB2-dependent’, meaning that ERBB2 signalling is indispensable for growth of these tumours." (PMID 18454161, 2008). "Many genes located close to ERBB2 on 17q12-q21 are known or suspected to play a role in carcinogenesis, and specifically, in breast carcinogenesis." (PMID 18702822, 2008). "The presence of membranous staining for EGFR and/or ErbB2 was significantly correlated with tumour phenotype." (PMID 17700572, 2007). "The prognostic component of the ER and ERBB2 status as well as different gene signatures were found to be strongly related to tumor proliferation." (PMID 17535433, 2007). "Among the 109 tumours used, 76 had been previously classified into the five reported molecular subtypes (i.e., luminal A, luminal B, basal-like, ERBB2, and normal-like), while 33 remained unclassified." (PMID 17338809, 2007). "Even though gene expression studies separate the basal-like tumors from the ERBB2 tumor subgroup, there are some immunohistochemically basal cytokeratin-expressing tumors that show HER-2 oncogene amplification." (PMID 17263897, 2007). "The luminal A and luminal B subtypes gather ER+ tumours, while the basal-like, ERBB2 and normal-like subclasses assemble ER- tumours." (PMID 17338809, 2007). "The ERBB2-overexpressing tumor cells BT474 and SkBr3 have high basal p-ERK1/2, and both showed a further increase in ERK1/2 activity in response to Wnt1." (PMID 17897439, 2007). "The RNase however becomes toxic when internalised in ErbB2-positive tumour cells, to which it is directed through its fusion with Erbicin." (PMID 17923870, 2007). "Tumours expressing low levels of ER or high levels of ERBB2 exhibited less reduction in Ki67 staining following AI treatment." (PMID 17555561, 2007).
tumor (continued). "As expected, the majority of the ERBB2 tumours (6 out of 8) were classified into subgroup 9, while the majority of the basal-type tumours (18 out of 20) were classified into subgroup 10." (PMID 17338809, 2007). "The basal-like group was subsequently defined, using immunohistochemistry, as being ER- PR- ERBB2-, with tumor cells expressing at least one basal-myoepithelial marker such as KRT 5/6 or KRT 14 in association with EGFR or KIT." (PMID 17417968, 2007). "Subgroup 10 (ERBB2 subtype) also included high SBR grade tumours (90% SBRIII), although these were both ER- (50%) and ER+ (50%)." (PMID 17338809, 2007). "These include patient age, tumor size, lymph node status, presence of distant metastasis (TNM-stage; tumor, node, metastasis), histological type, tumor grade, and estrogen receptor (ER), progesterone receptor (PR) and ERBB2/HER-2 status." (PMID 17504517, 2007). "Current prognostic factors (including lymph node status, tumour size, histological grade, hormone receptor status, ERBB2 expression and patient age) are insufficient to accurately predict the clinical outcome." (PMID 17338809, 2007). "Hyperactivation of MAPK was investigated using a recently described MAPK signature, and was linked to tumour phenotype, ER and EGFR and/or ErbB2 overexpression." (PMID 17700572, 2007). "Previous studies have shown that the effect of the Erbicin-derived compact antibody on tumour cell growth correlates with the lower ErbB2 levels generated by an increased receptor turnover as triggered by antibody binding." (PMID 17923870, 2007). "These clones were used to cluster the whole data set, which gave expected results separating basal/ER-, luminal/ER+ and ERBB2+/ER- tumor groups from each other similarly to the original study (data not shown)." (PMID 17263897, 2007). "Hyperactivation of MAPK was associated with both ER status and tumour phenotype by unsupervised hierarchical clustering using the MAPK signature and was significantly reflected by overexpression of EGFR and/or ErbB2." (PMID 17700572, 2007). "Not surprisingly, despite differences in receptor status, luminal B and ERBB2 share similar clinical – such as tumor grade – and prognostic characteristics." (PMID 16846532, 2006). "The average tumor size and the proportion of tumors smaller than 21 mm were not dramatically different among the groups, with the exception of the ERBB2 group, in which the tumor size tended to be larger." (PMID 16846532, 2006). "Even in the cases where GEPs of a CB and ST did not agglomerate, the expression levels of the ER and progesterone receptor as well as ERBB2 measured in the CB were also representative for the whole tumor." (PMID 16919157, 2006). "Two of the subtypes (luminal A and luminal B) belong to the estrogen receptor positive (ER+) group of tumours, while the tumours in the three other subgroups (basal-like, ERBB2+ and normal-like) in general, all are estrogen receptor negative (ER-)." (PMID 16536878, 2006). "Previous reports state that specific ErbB heterodimers, i.e., ErbB1/ErbB2 and ErbB2/ErbB3, result in increased tumor growth and cell proliferation." (PMID 16519802, 2006). "Multivariate Cox analysis was performed including P-Akt and those additional variables that were found to have significant prognostic value in univariate Cox models (ER, ErbB-2 and node status, and tumour size and grading)." (PMID 15987444, 2005). "The erbB2 results were very similar in the three groups of familial cases, with 18.6%, 15.1% and 17.4% of the BRCA1, BRCA2 and non-BRCA1/2 tumours, respectively, expressing the erbB2 antigen." (PMID 15642173, 2005). "At 6 days after the last vaccination, mice were challenged by s.c. injection of Renca-lacZ/ErbB2 cells into each flank, and tumour growth was followed." (PMID 15812545, 2005).